HGF (hepatocyte growth factor)
Diseases named in the same sentence as HGF in open-access papers (continued):
Sharing a sentence is not in itself a finding about the gene and the disease.
tumor (continued). "Meanwhile, HGF (hepatocyte growth factor) produced by CAFs, in turn, activates the MAPK and PI3K/AKT pathways in the tumor cells, leading to resistance to the treatments." (PMID 34885115, 2021). "Within a variety of tumor types and pathways, ADSCs produce numerous growth factors, including VEGF, HGF, and bFGF, which lead to increased vascularization." (PMID 34362454, 2021). "A prominent example is stromal mouse hepatocyte growth factor (HGF), which cannot fully activate the human MET receptor in epithelial cells, potentially limiting the growth of HGF-dependent tumours." (PMID 33435818, 2021). "It provided a robust TGI (tumor growth inhibition) in the MET-amplified GTL-16 model and a U87MG model exhibiting the HGF/c-MET autocrine loop." (PMID 35087755, 2021). "MAFs facilitate the metastatic tumor cell invasive phenotype in peritoneal metastases, possibly via TGF-β1, HGF and MMP2." (PMID 34112258, 2021). "Well-established signals that promote EMT in various tumor cell models are induced by TGF-β and growth factors including FGF, EGF and HGF." (PMID 33481051, 2021). "HGF-sustained MET-activation in cancer cells exacerbates their aggressiveness, prompting dissemination from the primary tumor to regional and distant sites." (PMID 34298732, 2021). "HGF/c-MET signaling pathway (type X TKR) regulates cell proliferation, motility, and survival, also being a mediator of tumor growth and neo-angiogenesis." (PMID 33916438, 2021). "On the other hand, HGF-MET signaling plays a role in cancer cells, conferring malignant features such as invasion, metastasis, and drug resistance in the tumor microenvironment." (PMID 34925346, 2021). "We examined levels of RTK ligands, HGF and NRG1, and found significant upregulation of these ligands in tumor tissue from erlotinib-treated mice in both A549 and HCC827 tumors." (PMID 34853306, 2021). "The adhesion of tumor cells to the peritoneum is promoted by activated MAFs via enhanced β2-integrin-dependent tumor cell-MAF interactions rather than exposure of the underlying matrix, which may also be mediated by TGF-β1, hepatocyte growth factor (HGF) and MMP2." (PMID 34112258, 2021). "MAFs are capable of promoting the proliferation of metastatic tumor cells by secreting factors, such as periostin, PDGF, HA and hepatocyte growth factor (HGF)." (PMID 34112258, 2021). "Non-anticoagulant heparin derivatives such as SST0001 or roneparstat significantly downregulated heparanase-dependent cleavage of syndecan-1 HS chains, attenuated HGF, VEGF, and MMP-9 expression resulting in decreased tumor growth and angiogenesisinvivo." (PMID 33800172, 2021). "The proto‐oncogene mesenchymal–epithelial transition (MET) tyrosine kinase and its ligand hepatocyte growth factor (HGF) play an important role in the migration, proliferation, and invasion of tumour cells." (PMID 34761497, 2021). "In HCC, the suppression of CYP1A2 stimulates HIF-1α upregulation and HGF synthesis to activate MET/PI3K/AKT/NF-κB signaling as well as MMPs, facilitating tumor growth, migration, and invasion." (PMID 33500715, 2021). "Although both IL-6 and HGF activate STAT3 and induce ZEB2, they seem to play a different role in tumor progression." (PMID 34408135, 2021). "Macrophages altered by tumor CCL5 expression and EVs have increased expression of several genes known to drive invasion and metastasis, including OPN, SLPI, HGF, and NRG3." (PMID 34298673, 2021). "Tumor angiogenesis is regulated by a variety of angiogenic factors such as vascular endothelial growth factor (VEGF), hepatocyte growth factor (HGF), transforming growth factor-beta (TGF-β), and hypoxia-inducible factor-1 (HIF-1)." (PMID 34513829, 2021). "One-week post-resection, mice were randomised to four treatments of 8 weeks: (i) IgG, (ii) gemcitabine (G), (iii) HGF/c-MET inhibition (HiCi) and (iv) HiCi + G. Tumour burden was assessed longitudinally by bioluminescence." (PMID 34199452, 2021).
tumor (continued). "In human malignancies, the HGF-MET pathway was found altered by several mechanisms, providing tumor cells the capacity to proliferate and disseminate." (PMID 33918490, 2021). "Rab GTPases regulate early endocytic transport of several growth factors that promote tumor cell invasion and metastasis, including epithelial growth factor (EGFR) and hepatocyte growth factor (HGF)." (PMID 34141705, 2021). "Analysis of the tumor EV-educated macrophages (TEMs) showed secretion of a variety of factors including CXCL1, CTLA-4, IFNG, OPN, HGF, TGFB, and CCL19 capable of remodeling the surrounding tumor stroma and immune infiltrate." (PMID 34298673, 2021). "These ECM proteins also store growth factors such as HGF, PDGF, TGF-β, CTGF, and VEGF, which influence the immunity escape of tumor environment." (PMID 34819565, 2021). "We also found a strong correlation between HGF levels, Ang-2, and VEGF levels, further supporting the fundamental value of these markers in tumor angiogenesis." (PMID 35008171, 2021). "In GBM, when HGF binds to MET and induces receptor dimerization and auto-phosphorylation, it triggers a cascade within the nucleus that signals for tumor growth, invasion, and metastasis." (PMID 34055785, 2021). "In the TME, tumor cells recruit immature DCs from the peripheral blood by releasing multiple cytokines (e.g., VEGF, β-defensin, CXCL12, HGF, and CXCL8), which lack the ability to inhibit tumor angiogenesis." (PMID 34294146, 2021). "Hepatocyte growth factor (HGF) is also highly expressed in CAFs and has been described to influence EMT and tumour survival-activating signalling pathways such as ERK and AKT in tumour cells." (PMID 34885024, 2021). "HGF present in the TME induce neutrophil recruitment and production of nitric oxide (NO), which results in killing of tumor cells." (PMID 34484197, 2021). "The subsequent uptake of soluble heparanase by tumor cells initiated ERK and Akt signaling pathways, stimulated the expression of vascular endothelial growth factor (VEGF), HGF, and MMP-9, and was correlated with an aggressive tumor phenotype." (PMID 33800172, 2021). "Another recent study has shown the tumor-promoting effect of myofibroblastic CAF-secreted hyaluronan and inflammatory CAF-secreted HGF, which is responsible for the CAF–HCC interaction loop." (PMID 34868982, 2021). "For instance, CAFs secrete growth factors such as CXCL12, HGF, EGF, IGF, IL‐6, IL‐8, IL‐11 and CCL5, which facilitate tumour growth." (PMID 33943003, 2021). "For example, HGF (hepatocyte growth factor) produced by CAFs activates and enhances PI3K/ATK signaling in the tumor cells, promoting cancer cell survival and resistance against treatments." (PMID 33621951, 2021). "In the tumor microenvironment, cancer cells secrete factors, such as TGF-β, hepatocyte growth factor (HGF), and platelet-derived growth factor (PDGF), activating changes in EMT." (PMID 34371753, 2021). "These MSCs produce hepatocyte growth factor (HGF) and tenascin C, which enhances tumor proliferation and promotes transformation into invasive phenotypes." (PMID 34957091, 2021). "Studies have shown that cytokines hepatocyte growth factor (HGF), epidermal growth factor (EGF), etc can enhance the phosphorylation of cortactin, promoting the tumour metastasis." (PMID 33191645, 2021). "Cancer cells also recruit macrophages to the tumor by secreting exosomes containing IL-8, VEGF, HGF, and CD44 mRNA that re-educate nearby monocytes, which differentiate into TAMs once they enter the tumor stroma." (PMID 34621752, 2021). "In mouse models, fibroblast-specific Prrx1 deletion led to more differentiated, less metastatic tumours, alongside changes to the tumour ECM, and this phenotype was attributed to release of hepatocyte growth factor (HGF) driving EMT in tumour cells." (PMID 34638468, 2021).
tumor (continued). "KCs also secrete hepatocyte growth factor (HGF), VEGF, and matrix metalloproteinases (MMPs) such as MMP-9 and MMP14 that promote tumour cell invasion in the parenchymal space as well as tumour cell proliferation and angiogenesis." (PMID 33669775, 2021). "Hepatocyte growth factor (HGF) and chemotactic factors are critical driving forces for tumor cell movement." (PMID 34956377, 2021). "Once the tumor is established, ECs not only form the blood vessels that supply oxygen and nutrients to tumoral cells, but also communicate with them via angiocrine factors such as HGF and ICAM-1, which promote tumor progression." (PMID 35008212, 2021). "The HGF/c-MET signaling pathway regulates downstream PI3K/Akt/mTOR, Ras/MAPK, and JAK/STAT signaling pathways, which are important in regulating tumor cell growth, migration, and invasion." (PMID 34408780, 2021). "McCarty reported that tumor cell proliferation and invasion are regulated by cross‐talk between the VEGF and HGF signaling pathways." (PMID 33543833, 2021). "MSCs have been found to release many soluble factors that promote tumor survival and its proliferation, including VEGF, FGF-2, PDGF, HGF, BDNF, SDF-1α, IGF-1, IGF-2, TGF-β, and IGFBP-2." (PMID 34112253, 2021). "Our findings identify miR-144/miR-451a cluster as a tumor suppressor in HCC, which induce M1-like repolarization of TAMs though paracrine pathway via targeting HGF and MIF." (PMID 33658044, 2021). "By investigating the expression profiles of HGF and c-MET in all tumors in the TCGA database, we selected 11 solid tumors with significant differences in HGF or c-MET expression between tumor and normal tissues." (PMID 34261467, 2021). "LncRNA DEAD/H box protein 11 antisense RNA 1 (DDX11-AS1) directly binds to tumor-suppressive miR-195-5p, thus allowing MACC1, a key regulator of the hepatocyte growth factor-HGF receptor (HGFR) pathway, to be overexpressed in HCC." (PMID 33652661, 2021). "CAF's are able enhancer of tumour invasion through their secretion of TNC-c, TNC-w, HGF, and MMPs along with TGF-β27." (PMID 33739025, 2021). "The HGF-MET axis orchestrates cell morphology and wound healing in a physiological state, but in cancer, it regulates crucial pathways for tumor growth and metastasis through Ras-MAPK, PI3K, FAK-Src, and STAT3 signaling." (PMID 34037097, 2021). "For example, as a tumor inhibitor, CYP1A2 suppressed tumorigenicity by inhibiting HGF/MET and reduced the sensitivity of sorafenib via inhibiting the NF-kB signaling." (PMID 34900444, 2021). "Immunohistochemical expression of c-Met, HGF, VEGFR2, and MVD was assessed in tumor specimens of GBM patients treated with bevacizumab, after progression under temozolomide." (PMID 33727583, 2021). "Extensive experimental and clinical data provide several lines of evidence that HGF and its cognate receptor MET are crucial components of various diseases including organ fibrosis and tumor progression." (PMID 34128105, 2021). "Multiple signaling pathways such as HGF/c-Met, miR20b, and IGF1/IGFBP2 are involved in the process of ADSCs promoting tumor cell proliferation." (PMID 33407902, 2021). "Peri-tumor fibroblasts can also facilitate intrahepatic metastasis via SCGF-β- and HGF-mediated signaling pathways." (PMID 34868982, 2021). "IL1A is one of the prominent inflammatory cytokines and contributes to tumor invasion, angiogenesis, and metastasis by inducing VEGF, TNF-α, HGF, and TGF-β." (PMID 34203721, 2021). "In cancer models, it was proven that HGF/c-MET is responsible for the resistance to anti-VEGF therapy with sunitinib (VEGFR and PDGFR RTKi), while the concomitant exposure to HGF/c-MET inhibitors and sunitinib abrogated angiogenesis and tumor growth." (PMID 33916438, 2021).
tumor (continued). "In pancreatic neoplasms, the HGF/c-Met axis is involved in the intricate tumor-stroma crosstalk, GEM-resistance in vivo, and metastasis of therapy-resistant tumor cells." (PMID 34453639, 2021). "Neutrophilia inhibits the cytolytic activity of immune cells and increases the production of factors that promote tumor growth, such as VEGF and hepatocyte growth factor." (PMID 32316940, 2020). "We next measured the cMet–HGF complex as a measure of cMet activation as well as total cMet and total HGF using the VeraTag assay in FFPE tumor tissue." (PMID 32545260, 2020). "TAMs are recruited to the tumor site through tumor secretion of cytokines and chemokines, including ATP, CSF-1, CCL2, GDNF, GM-CSF HGF/SF, MCF-3, SDF-1, TNF and VEGF6,15." (PMID 32555306, 2020). "One such RTK possibly involved in the DDR is MET, the RTK for hepatocyte growth factor (HGF) which is deregulated in abundance and/or activity in a variety of human tumor types and serves as an oncogenic target." (PMID 32336009, 2020). "CAFs secrete various growth factors such as TGF-β, HGF, FGF and chemokine CXCL12/SDF-1 (C-X-C motif chemokine ligand 12 or Stromal cell-derived factor 1), which together promote tumour growth, EMT and invasion in cancer cells." (PMID 32824003, 2020). "c-Met is a receptor tyrosine kinase for hepatocyte growth factor (HGF) and plays a critical role in embryonic development, tissue repair, and tumor progression." (PMID 32028611, 2020). "Preosteoblasts and osteoblasts express tumor-promoting osteoprotegerin (OPG), hepatocyte growth factor (HGF), and secrete connective tissue growth factor (CTGF) and TGFβ." (PMID 33162934, 2020). "Induction of high serum HGF levels by CLP promoted liver metastases in a murine liver metastasis model, suggesting the involvement of the HGF/c-Met signaling pathway in tumor promotion mechanisms." (PMID 32630328, 2020). "In another study, recombinant human HGF was labeled with 64Cu, and this probe had strong and specific binding to c-Met in a U87MG tumor model (right)." (PMID 33193439, 2020). "In our review, the potential roles of the HGF/c-Met axis in other hallmarks of HCC, such as interactions with tumor microenvironment and drug resistance, are also highlighted." (PMID 32083078, 2020). "After c38 tumor cell inoculation, significantly less active EGFR, PDGF-Rα and HGF/MSPR receptors were detected in the livers of pLIVE-DCN animals compared to pLIVE-0 mice (p value < 0.05)." (PMID 32824864, 2020). "Deregulated expression of RTKs and related growth factors such as VEGF, HGF, and PDGF can result in specific signaling that enhances tumor growth." (PMID 33066121, 2020). "Activation of Met upon binding to its ligand, hepatocyte growth factor (HGF), can drive EMT and tumour metastasis." (PMID 32873152, 2020). "DYNLL1-related cytoskeletal rearrangement and tumor cell migration can be theoretically inhibited by anti-HGF therapy, as DYNLL1 shows indirect interaction with HGF in HGF/c-MET pathway in HNSCC." (PMID 32564264, 2020). "An established tumor-intrinsic resistance mechanism is cross-talk between the EGFR and hepatocyte growth factor (HGF)/cMet pathways." (PMID 32545260, 2020). "At the cellular level, the HGF/MET pathway promotes tumorigenesis through stimulating cell cycle progressions, tumor cell migration, invasion, angiogenesis, and through inhibiting tumor apoptosis." (PMID 33066121, 2020). "CAFs can secrete ECM components (such as type I collagen or fibrin) and several soluble factors, such as growth factors (EGF, HGF, TGF-β), metalloproteinases (MMP-1, -2, -9) or chemokines (CXCL12), to promote tumor growth and metastasis." (PMID 32984031, 2020). "Specifically, CAFs produce elevated levels of hepatocyte growth factor (HGF), which increases tumor cell proliferation, invasion, migration, and chemoresistance." (PMID 32756436, 2020).
tumor (continued). "The proto-oncogene MET, the hepatocyte growth factor (HGF) receptor, is a transmembrane receptor tyrosine kinase (RTK) with a prominent role in tumor metastasis and resistance to anti-cancer therapies." (PMID 32659961, 2020). "Targeting HGF/MET induces tumor cell apoptosis through cell-cycle arrest and DNA damage and suppresses tumor progression." (PMID 32001707, 2020). "In a similar model, the complement 3a (C3a) protein secreted by CAFs induces an autocrine loop that stimulates PI3K/Akt signaling and the secretion of TGF-β, HGF and PDGF that promote EMT, invasion and lung metastasis in tumor cells." (PMID 33114328, 2020). "CAFs secrete multiple angiogenic molecules like VEGF, PDGF, CXCL-12 or HGF that promote ECM remodeling, the proliferation of ECs and the recruitment of ECs and pericytes to the tumor." (PMID 33114328, 2020). "MDSCs also produce cytokines such as hepatocyte growth factor (HGF) and oncostatin M (OSM), which are pro-metastatic via induction of an invasive phenotype and detachment of tumor cells, respectively." (PMID 32244751, 2020). "By observing the effects of HGF, c‐MET amplification, and EGFR‐T790M tumor on PD‐L1 expression and immune escape ability before and after EGFR‐TKIS drug resistance, the regulation mechanism of PD‐L1 in different drug‐resistant subtypes was discussed." (PMID 32875727, 2020). "It has been demonstrated that the binding of hepatocyte growth factor (HGF), a growth factor secreted from tumor cells or surrounding interstitial tissue, to the HGF receptor (MET) induces the autophosphorylation of MET." (PMID 31820255, 2020). "Thus, the serum HGF concentration may be helpful as a tumor biomarker for HCC." (PMID 32117981, 2020). "For example, deguelin can suppress tumor angiogenesis on vascular endothelial cells by decreasing autocrine VEGF and repressing HGF-induced c-Met signaling pathways, thereby inhibiting HCC progression." (PMID 32117981, 2020). "Important factors regulating the metastatic behavior of different tumor types, including RMS, are hepatocyte growth factor (HGF) and stromal-derived factor-1 (SDF-1)." (PMID 32664538, 2020). "This study showed that HOTAIR epigenetically repressed miR-34a by binding to PRC2, and then activated the HGF/C-Met/Snail pathway, which resulted in EMT and accelerated GC tumor metastasis." (PMID 32219093, 2020). "SF/HGF and its receptor tyrosine kinase c-MET are expressed in brain tumors and were shown to promote tumor proliferation, migration, invasion, and angiogenesis." (PMID 32152825, 2020). "There is evidence that neutrophils and other immune cells, such as macrophages, have the capability to secrete cytokines and tumor growth promoting factors, including VEGF, HGF, IL-6, IL-8, matrix metalloproteinases, and elastases." (PMID 32325965, 2020). "The resulting tumor interactome network highlighted several recurring modules, including a large matrix remodeling module, modules centered around ERBB, HGF‐MET, TGFbeta, FGF, IGF, and VEGFA, a lipid trafficking module, and a WNT planar cell polarity module." (PMID 33332768, 2020). "All this leads to the senescence of cells that then release growth factors, the most important of which is hepatocyte growth factor (HGF), into the tumour microenvironment, leading to the accelerated growth of neighbouring tumour cells." (PMID 32370077, 2020). "Beside TGFβ1, CAF secrete strong mitogenic factors for HCC cells, such as hepatocyte growth factor (HGF) and epiregulin that promote tumor growth." (PMID 32899119, 2020). "It was also found that patients with higher levels of HGF in the serum showed shorter survival times than patients with lower levels of the factor, which indicates that the concentration of HGF in the serum may be a useful indicator of the stage of neoplastic disease and the related outcomes." (PMID 32607415, 2020).